AXL (AXL receptor tyrosine kinase)
Diseases named in the same sentence as AXL in open-access papers (continued):
Sharing a sentence is not in itself a finding about the gene and the disease.
ovarian carcinoma (continued). "We describe here the in vitro and in vivo activity of a PronectinTM AXL-targeted first-in-class bispecific T cell engager (pAXLxCD3ε) against Epithelial Ovarian Cancer (EOC)." (PMID 37143061, 2023). "In particular, in ovarian cancer AXL is upregulated in advanced stage and in metastases as compared with normal ovarian tissue." (PMID 37143061, 2023). "By binding to Dice, PRKRA downregulated the expression of miRNA-515-3p, leading to the up-regulation of target gene AXL and oxaliplatin resistance of ovarian cancer." (PMID 37484321, 2023). "In particular, AXL was recognized as a mediator of drug resistance in ovarian cancer cell lines that acquired resistance to cisplatin." (PMID 35572601, 2022). "Especially, with regard to EMT process, several articles demonstrated the important roles of m6A regulation on SNAI1 in HeLa and HepG2 cells, GFI1 and ZMYM1 in gastric cancer cells, AXL in ovarian cancer cells, and ZBTB1 in bronchial epithelial cells." (PMID 36183833, 2022). "METTL3 can promote the proliferation and migration of ovarian cancer cells by regulating the transcription of AXL." (PMID 34497267, 2021). "Recent studies indicate that METTL3 expression correlates with ovarian carcinoma cellular proliferation and migration through the regulation of AXL transcription." (PMID 34497267, 2021). "In ovarian cancer cells, the interaction between AXL and EGFR family members or cMET is stimulated by GAS6." (PMID 34638349, 2021). "AXL is overexpressed in several cancers, including gastric, breast, colorectal, prostate and ovarian cancers." (PMID 34442532, 2021). "In parallel, combined treatment with VS-6766/CH5126766 and AXL inhibitor (bemcentinib) has provided a stronger blockage of tumor growth in KRAS-mutant ovarian cancer cells with overexpressed AXL." (PMID 34946644, 2021). "Hua’s group unveiled that methyltransferase-like 3 (METTL3) was up-regulated in ovarian cancer and promoted growth and invasion of ovarian cancer cells via stimulating the receptor tyrosine kinase AXL translation." (PMID 34616622, 2021). "The upregulated expression of tyrosine kinase AXL has been reported in several hematologic and solid human tumors, including gastric, breast, colorectal, prostate and ovarian cancers." (PMID 34442532, 2021). "Therapeutically, p85β expression renders ovarian cancer cells vulnerable to inhibitors of AXL, p110, or PDK1." (PMID 32385243, 2020). "Here we report that p85β upregulates the protein level of the receptor tyrosine kinase AXL to induce oncogenic signaling in ovarian cancer." (PMID 32385243, 2020). "Together, our findings provide a rationale for pharmacological blockade of the AXL signaling axis in PIK3R2-amplified ovarian cancer." (PMID 32385243, 2020). "We also investigated the in vivo antitumor effect of AXL inhibition (TP-0903) on p85β-overexpressing or vector control-expressing DOV13 ovarian cancer xenografts, which reproduced serous histology consistent with its origin and previous report." (PMID 32385243, 2020). "Here the authors show that p85β promotes AXL protein stability, which in turn activates p110 to induce PDK1/SGK3 signaling, and therapeutically, p85β-expressing ovarian cancer cells are sensitive to AXL inhibition." (PMID 32385243, 2020). "AXL inhibition by BGB324 (R428/Bemcentinib) increased response to chemotherapy in a patient-derived xenograft model from a chemoresistant ovarian cancer." (PMID 31694201, 2019). "In ovarian cancer, AXL expression was significantly higher in chemoresistant ovarian tumors, compared to chemosensitive cancers." (PMID 31694201, 2019).
ovarian carcinoma (continued). "We next treated ARK1 uterine serous cancer cells and OVCAR8 ovarian cancer cells with buffer, AXL siRNA (siAXL) alone, p5RHH-scrambled siRNA nanoparticles (p5RHH-siControl), or p5RHH-siAXL siRNA nanoparticles and evaluated protein expression after 72 hours." (PMID 30886159, 2019). "Lentiviral knockdown of AXL expression in metastatic ovarian cancer cell lines increased sensitivity to the chemotherapeutic agents paclitaxel and carboplatin in vitro." (PMID 31694201, 2019). "Previous study also reported that tumor suppressor OPCML inactivates AXL-dependent oncogenic signaling in ovarian cancer and also prevent transactivation of other RTKs such as EGFR and cMET44." (PMID 31043587, 2019). "In ovarian cancer another target of miR-34a is AXL, a tyrosine kinase receptor with oncogenic properties." (PMID 26879132, 2016). "Downregulation of AXL through the IL6/STAT3 pathway resulted in overcoming taxol resistance in ovarian cancer cells." (PMID 27590506, 2016). "AXL inhibition via soluble AXL receptors in vivo has also been shown to reduce ovarian cancer metastasis in mice with established disease by 63%." (PMID 27764792, 2016). "We were particularly interested in the PI3K/AKT pathway because AXL has been reported to regulate ovarian cancer metastasis through this pathway." (PMID 27764792, 2016). "As in ovarian cancer, reduction of AXL expression primarily reduced the establishment of new metastatic lesions during progression of EC metastasis rather than reducing proliferation of the established tumors themselves." (PMID 27764792, 2016). "A large body of evidence suggested that the activation of AXL is associated with TKI-resistance in several cancers, such as gastrointestinal stromal tumors, ovarian cancer, triple-negative breast cancer and chronic myeloid leukemia." (PMID 25760142, 2015). "AXL knockdown also inhibited the size and the number of metastases in a xenogeneic mouse model of ovarian cancer metastasis." (PMID 23878800, 2013). "AXL protein expression was found to be significantly higher in ovarian carcinomas than in ovarian epithelium, and knockdown of AXL in SKOV3 cells also reduced the expression of MMP-1 and MMP-9, which contribute to tumour cell invasion." (PMID 23878800, 2013). "EGFR, MET, and AXL activation in the ovarian cancer lines was comparable to that in MESO924 cells, which are known to feature strong activation of these RTK." (PMID 21962244, 2011). "Herein, we demonstrate co-activation of multiple RTKs (EGFR, ERBB2, ERBB4, MET and/or AXL) in individual ovarian cancer cell lines and primary tumors." (PMID 21962244, 2011). "The HSP90 inhibition led to the dephosphorylation and degradation of EGFR, ERBB2, ERBB4, MET and AXL in various ovarian cancer cells." (PMID 21962244, 2011). "Our studies demonstrated that simultaneous activation of multi-RTKs including EGFR, ERBB2, MET, and AXL contributes to ovarian cancer cell proliferation and survival." (PMID 21962244, 2011). "Inhibition of total EGFR, ERBB2, MET and AXL expression was seen in all ovarian cancer cell lines after treatment with 17-AAG in serum-containing medium for 48 hours." (PMID 21962244, 2011). "Our results suggested that the simultaneous activation of multi-RTK (EGFR, ERBB2, ERBB4, MET and/or AXL) in individual ovarian cancer contribute to the drug resistance to individual RTK inhibitors in ovarian cancer." (PMID 21962244, 2011). "In the current studies we demonstrate the simultaneous activation of multiple RTKs - including EGFR, ERBB2, MET, and/or AXL - in individual ovarian cancer cell lines and primary tumors." (PMID 21962244, 2011). "When AXL is complexed with its ligand GAS6 in ovarian cancer cells, OPCML chaperones the AXL-GAS6 complex into external membrane lipid-raft domains where the complex becomes dephosphorylated through apposition to a raft restricted phosphatase and then targeted for ubiquitin-dependent degradation." (PMID 40699804, 2025).
ovarian carcinoma (continued). "AXL expression is elevated in specific ovarian cancer subtypes and plays a role in tumor progression and therapy resistance, although expression levels may vary depending on tumor context." (PMID 41347223, 2025). "Interestingly, more recent data indicate that AXL expression exhibits variation across monolayer and/or spheroid ovarian cancer cells models." (PMID 37143061, 2023). "Inhibition AXL could promote the chemosensitivity to cancer cells, especially platinum and taxane in ovarian cancer." (PMID 35769811, 2022). "Similarly, METTL3 also drove proliferation in ovarian cancer through regulation of the receptor tyrosine kinase AXL; however, the regulatory mechanism by which METTL3 up-regulates AXL was not established." (PMID 35350378, 2022). "As for AXL, there were lots of researches focused on ovarian cancer, especially in chemoresistance." (PMID 35769811, 2022). "Moreover, metformin treatment of ovarian cancer cells significantly decreased both mRNA and protein levels of Axl and Tyro3 in a dose-dependent manner, indicating that metformin suppresses AXL and TYRO3 expression at the transcriptional level." (PMID 36361682, 2022). "Importantly, siRNA-mediated inactivation of AXL was also sufficient to block the internalization of GAS6 in ovarian cancer SKOV3 cells that express all three TAM receptors." (PMID 35622156, 2022). "Furthermore, the fact that in vivo suppression of tumorigenicity was lost with P95R indicated the biological importance of the AXL pathway in ovarian cancer despite an intact FGFR1/FGF1 axis." (PMID 31316070, 2019). "Since the therapeutic targeting of AXL inhibits tumor growth and metastasis in ovarian cancer models, it is likely that AXL may become a potential therapeutic target in colitis-associated colorectal cancer." (PMID 30140167, 2018). "In two models of intraperitoneal ovarian cancer, the AXL-DNA-APTAMER suppresses metastasis, migration/invasion and tumor growth on its own and enhances the effects of paclitaxel treatment, presumably by disrupting focal adhesion kinase (FAK) phosphorylation and matrix-metalloproteinases." (PMID 28703779, 2017). "In vivo, AXL signaling promotes metastasis in breast, glioma, lung, and ovarian cancer." (PMID 27764792, 2016). "If the GAS6/AXL axis is also involved in chemoresistance in ovarian cancer, targeting this pathway may sensitise tumours to paclitaxel and carboplatin, the current mainstays of therapy, whilst also directly inhibiting tumour growth." (PMID 23878800, 2013). "AXL overexpression and/or activation has been linked with resistance to chemotherapy in gastrointestinal stromal tumor cell lines, in CML cells, rhabdomyosarcoma, HER-2 positive breast tumor cells and ovarian cancer." (PMID 22141136, 2011). "Co-overexpression of AXL with Gas6 has also been reported in several types of tumors including ovarian cancer, and may therefore have an important role in uncontrolled cell growth/proliferation." (PMID 19055724, 2008). "Moreover, the role of the GAS/AXL pathway in DDR has gradually been revealed in ovarian cancer." (PMID 38539161, 2024). "Consistently with these findings, AXL genetic or pharmacological inhibition in ovarian cancer led to impaired migration and metastasis and in increased chemo-sensitivity of both patient derived xenograft and ovarian cell lines and could therefore represent a promising therapeutic target in EOC." (PMID 37143061, 2023). "In ovarian cancers, OPCML drives inactivation and degradation of the RTKs HER2, HER4, FGFR1, FGFR3, EPHA2, and AXL, and the specificity of this network is underscored by identification of a group of RTKs that are unaffected by OPCML." (PMID 40699804, 2025). "In ovarian cancer cell lines, OPCML enhanced the effect of the the AXL inhibitor bemcentinib both in vitro and in vivo." (PMID 40699804, 2025).
ovarian carcinoma (continued). "The GAS6/AXL pathway also confers resistance through interactions with other signaling pathways, such as the PI3K, JAK/STAT and MAPK pathways, in ovarian cancer." (PMID 38539161, 2024). "For instance, inhibition of AXL reduces the phosphorylation of M2 isoform of pyruvate kinase (PKM2) at Y105, which decreases glycolysis and enhances chemosensitivity of human ovarian cancer cells to cisplatin." (PMID 37328828, 2023). "Inhibition of GAS6/AXL axis reduces RAD51 foci and increase 53BP1 foci, inhibiting homologous recombination (HR) and increasing the sensitivity of ovarian cancer to carboplatin." (PMID 37328828, 2023). "In ovarian carcinoma cells, upon GAS6 activation, AXL was reported to co-cluster with and transactivated MET, EGFR, and HER2, resulting in downstream activation of ERK." (PMID 35572601, 2022). "In our study, we found the signature-related genes such as AXL, FZD5, POLR3H, and MED1 were related to the immune cell expressions in ovarian cancer." (PMID 35769811, 2022). "In ovarian cancer, METTL3 activity has been reported to accelerate cell proliferation and migration by regulating transcription of AXL receptor tyrosine kinase (AXL, referring to the Greek term “anexelekto”, which means uncontrolled)." (PMID 34497267, 2021). "Here we report that p85β signals through its upstream kinase AXL, which in turn activates p110 to induce PDK1/SGK3 signaling, establishing the mechanistic basis for targeting AXL in PIK3R2-amplified ovarian cancer." (PMID 32385243, 2020). "This study investigated the expression levels of AXL, GAS6, Claudin-1, and Cofilin-1, as genes involved in EMT in relation to clinicopathologic features in ovarian cancer patients." (PMID 31700829, 2019). "Synergistic effects were observed in ID8 tumor-bearing mice, a model of ovarian cancer, when anti-PD1 antibodies and AXL inhibitors were combined (R428 and SGI-7079)." (PMID 31694201, 2019). "AXL is often expressed together with GAS6 in a variety of human cancers, often being highly expressed in advanced stage human breast and ovarian cancer." (PMID 22570691, 2012). "In mesenchymal subtype ovarian cancer cell lines, crosstalk between GAS6 activation of AXL and receptor tyrosine kinases (HER2 and MET) and its downstream signalling served specifically to enable cell mobility in mesenchymal cells, a feature absent from other molecular subtypes." (PMID 40696160, 2025). "In addition, the localization and expression of AXL and VEGFR exhibit significant variation between monolayer and spheroid ovarian cancer models." (PMID 39924521, 2025). "In terms of protein expression, we found that AXL was significantly up‐regulated in renal clear cell carcinoma, CD47 was significantly up‐regulated in ovarian cancer, pancreatic cancer and endometrial cancer, and MERTK was significantly up‐regulated in both ccRCC and pancreatic cancer." (PMID 40576208, 2025). "Likewise, in ovarian carcinoma, cytoplasmic METTL3 promotes AXL translation, contributing to the initiation and progression of ovarian cancer." (PMID 38444581, 2024). "METTL3 was shown to promote ovarian cancer cell proliferation, invasion, and migration through targeting pri-miRNA 126-5p, lncRNA RHPN1 antisense RNA 1 (head to head) (RHPN1-AS1) and AXL receptor tyrosine kinase (AXL) mRNA18,43,44." (PMID 38714753, 2024). "Furthermore, while AXL expression enhances the pro-apoptotic effect of metformin in EAC cells, this metformin-induced effect is attenuated by AXL expression in ovarian cancer cells." (PMID 35936716, 2022). "In ovarian cancer, AXL could promote glycolysis mediated by phosphorylating PKM2 at Y105, thus inhibiting the chemoresistance of ovarian cancer cells to cisplatin." (PMID 35769811, 2022). "Additionally, metformin has been shown to reduce mRNA and protein expression of AXL and TYRO3 receptor tyrosine kinases to overcome chemoresistance in human ovarian cancer cells." (PMID 35936716, 2022).
ovarian carcinoma (continued). "This study suggests that combined therapy strategies targeting AXL, like AZD7763, could improve responses in drug-resistant solid tumors where AXL is involved, such as NSCLC, BC, ovarian cancer, and others." (PMID 34884835, 2021). "AXL expression analysis in 87 mesothelioma patients showed that AXL expression was stronger in mesothelioma (MESO) than in most cancer types, including ovarian cancers, NSCLC, colon adenocarcinoma, and so on, confirming our previous immunoblotting observations." (PMID 32992696, 2020). "We found that AXL and MERTK were expressed at higher levels in liver tissue, lung tissue, endometrial tissue; CD47 was up‐regulated in breast tissue, lung tissue, ovarian cancer, pancreatic cancer and endometrial cancer; and HAVCR2 showed higher expression in renal clear cell carcinoma." (PMID 40576208, 2025). "Additionally, AXL has been shown to regulate MMP-1, MMP-2 and MMP-9 expression in ovarian cancer." (PMID 27764792, 2016). "This study provides more support that AXL may inhibit invasion but not proliferation as seen in ovarian cancer." (PMID 27764792, 2016). "A natural product, apigenin, reduced AXL expression in ovarian cancer cell lines without affecting IL6 production and STAT3 phosphorylation, suggesting the selectivity of the STAT proteins in the regulation of AXL expression." (PMID 36835239, 2023).